COBLL1 (cordon-bleu WH2 repeat protein like 1)
Synonyms: KIAA0977; COBLR1
Tractability: PROTAC: ubiquitination databases record sites on it; its protein half-life has been measured.
Gene: Protein-coding gene on chromosome 2 (164,653,624 to 164,843,679, reverse strand). Ensembl gene ENSG00000082438.
Subcellular location (Human Protein Atlas): Cell Junctions
Gene Ontology:
Molecular function: cadherin binding; protein binding; actin binding; actin monomer binding
Cellular component: extracellular exosome; cell cortex; membrane
Genetic constraint (gnomAD): Loss-of-function variants: 33 observed, 66.43 expected, observed/expected ratio (o/e) 0.5, 90% interval 0.38 to 0.66. The upper end of that interval is the gene's LOEUF score, 0.66, which puts it in group 2 of 6, group 1 being the genes least tolerant of losing a copy. Missense variants: 1,170 observed, 1,201.9 expected, observed/expected ratio (o/e) 0.97, 90% interval 0.93 to 1.02. Synonymous variants: 396 observed, 430.12 expected, observed/expected ratio (o/e) 0.92, 90% interval 0.85 to 1.
Homologues: Orthologues: chimpanzee COBLL1 (99% identical), macaque COBLL1 (95% identical), pig COBLL1 (78% identical), rabbit COBLL1 (77% identical), dog COBLL1 (75% identical), guinea pig COBLL1 (72% identical), mouse Cobll1 (69% identical), rat Cobll1 (66% identical), tropical clawed frog cobll1 (38% identical), zebrafish cobll1a (16% identical), zebrafish cobll1b (12% identical). Paralogues in human: COBL (21% identical).
Diseases named in the same sentence as COBLL1 in open-access papers:
COBLL1 is named in the same sentence as 35 diseases in open-access papers, as found by Europe PMC text mining. Sharing a sentence is not in itself a finding about the gene and the disease. The quoted sentences say what the papers report.
Obesity (10 papers, 2017 to 2025). Accumulation of substantial excess body fat. "We further investigated the association between COBLL1 rs6717858 genotypes and incidence of obesity, stratified by dietary fat intake (<15% vs. ≥15%)." (PMID 36835164, 2023). "Previous studies have also identified numerous genetic loci and gene variants such as FTO, MC4R, ADAMTS9 and GRB14/COBLL1, which have been found to be associated with overweight/obesity and diabetes." (PMID 38089629, 2023). "COBLL1 rs6717858 is associated with plasma leptin levels secreted from adipose tissue and obesity-related factors, such as body mass index (BMI), central obesity, waist circumference (WC), fat mass, and lipid levels (prominent effect in women)." (PMID 36835164, 2023). "This study aimed to determine the association between COBLL1 gene, dietary fat, and incidence of obesity." (PMID 36835164, 2023). "The COBLL1 gene is associated with abdominal obesity, BMI, fat mass, WC, waist-to-hip ratio, and blood lipids, and influences obesity risk by inhibiting lipid storage in adipose tissue." (PMID 36835164, 2023). "Decreased COBLL1 expression affects obesity and dyslipidemia risk by increasing lipid storage in adipose tissue." (PMID 36835164, 2023). "Mediation analyses were used to determine the causal relationship between SNPs, AT GRB14/COBLL1 mRNA expression, and obesity-related traits." (PMID 35955692, 2022). "The COBLL1 gene has been shown to be associated with body fat percentage and obesity, with subsequent metabolic and cardiovascular complications." (PMID 36009479, 2022). "Our study focused on a WHR-associated locus harboring two candidate genes, GRB14 and COBLL1, in the context of effects on obesity, fat distribution, and metabolic parameters." (PMID 35955692, 2022). "COBLL1 genetic variants and dietary fat intake had different sex-dependent effects in obesity." (PMID 36835164, 2023). "Therefore, this study aimed to examine the interaction between COBLL1 genetic variants and dietary fat in obesity using urban–rural prospective cohort data." (PMID 36835164, 2023). "We hypothesize that GRB14/COBLL1 may act as the causal genes for FD-related SNPs (rs10195252 and rs6738627), and that they may be regulated by SNP to effect obesity-related metabolic traits." (PMID 35955692, 2022). "Our findings showed that the influence of fat intake on the incidence of obesity differs according to the COBLL1 rs6717858 genotypes and sex." (PMID 36835164, 2023). "The effects of the COBLL1 rs6717858 genotypes and dietary fat on incidence of obesity were evaluated using multivariable Cox proportional hazard models." (PMID 36835164, 2023). "In terms of the percentage of energy from dietary fat (< 15% vs. ≥ 15%), our study also shows that the incidence of obesity differs according to the COBLL1 rs6717858 genotypes and sex." (PMID 36835164, 2023). "First, to our knowledge, it was the first to investigate the interaction between COBLL1 rs6717858 genotypes and dietary fat in obesity based on sex in a follow-up study." (PMID 36835164, 2023). "In conclusion, we present new information on the interaction between dietary fat and COBLL1 in obesity among middle-aged Korean adults." (PMID 36835164, 2023). "Controlling leptin levels by COBLL1 gene expression contributes to the influence of a HF diet in obesity." (PMID 36835164, 2023). "Several studies have examined the individual effects of the COBLL1 gene and dietary fat intake in obesity." (PMID 36835164, 2023). "In this study, the incidence of obesity for the COBLL1 rs6717858 genotypes differed according to sex, suggesting an effect on sex hormones." (PMID 36835164, 2023). "Although GWAS have suggested COBLL1 as a potential determinant of obesity, T2D, and impaired lipid metabolism, functional data are rather scarce to date." (PMID 35955692, 2022). "However, only few studies have investigated the interaction between dietary fat and the COBLL1 gene in obesity." (PMID 36835164, 2023).
Obesity (continued). "The association between the COBLL1 rs6717858 genotypes and the incidence of obesity based on sex was not significant." (PMID 36835164, 2023). "In contrast to GRB14, the link between obesity related traits and COBLL1 is less clear." (PMID 35955692, 2022). "Both vis and sc GRB14/COBLL1 gene expression correlate with T2D, but vis GRB14 expression is more of a risk factor for glucose metabolism because its mRNA expression is associated with HbA1c, FPG, and T2D independently of obesity." (PMID 35955692, 2022). "For example, of the four loci discovered by the recently discussed GWAS in BF% (in or near COBLL1/GRB14, IGF2BP1, PLA2G6, CRTC1) and in the most recent GWAS of obesity as measured by BMI only a very small number of these overall obesity loci exhibited sexual dimorphism (approximately 3–5%)." (PMID 28073971, 2017). "Here, we report significantly higher expression of COBLL1 and GRB14 in vis AT in patients with T2D, which seems to be independent of obesity." (PMID 35955692, 2022). "It must be acknowledged that despite the clear evidence for strong correlations between COBLL1 and GRB14 mRNA expression levels in AT and metabolic traits related to obesity, the observed findings do not allow for drawing any conclusions regarding causal relationships between these entities." (PMID 35955692, 2022).
Insulin resistance (8 papers, 2013 to 2024). Increased resistance towards insulin, that is, diminished effectiveness of insulin in reducing blood glucose levels. "An association among COBLL1 rs7607980 C allele, lower serum insulin levels, and lower insulin resistance was reported in overweight and obese children." (PMID 35626321, 2022). "An association between the COBLL1 rs7607980 C allele, lower serum insulin levels, and lower insulin resistance in overweight and obese children has also been indicated." (PMID 36009479, 2022). "Top loci in this cluster included several well-known associations with WHRadjBMI and insulin resistance including COBLL1, RSPO3, PPARG, and DNAH1012,47,54,55." (PMID 35773277, 2022). "The aim of the study was to investigate if the association between COBLL1 rs7607980 genetic variant and lower insulin resistance was present early in life." (PMID 23463496, 2013). "In the current report, we show for the first time an association between COBLL1 rs7607980 C allele, lower insulin levels and lower insulin resistance in overweight and obese children." (PMID 23463496, 2013). "In conclusion, we show for the first time the association between COBLL1 rs7607980 C allele, lower insulin levels and lower insulin resistance in overweight and obese children." (PMID 23463496, 2013). "A recent genome-wide association study on insulin resistance carried out in a large sample of adult individuals identified for the first time a common nonsynonymous variant (rs7607980) in the COBLL1 gene to be associated with lower insulin resistance." (PMID 23463496, 2013). "We show that the association between the COBLL1 C allele and lower insulin resistance is present already in young individuals (mean cohort age: 10 years)." (PMID 23463496, 2013). "Recently, a genetic variation (rs7607980) in the COBLL1 gene has been associated with lower insulin resistance in adults." (PMID 23463496, 2013). "The COBLL1 gene may also be associated with insulin resistance in human preadipocytes and adipocytes, and involved in metabolic syndrome and inflammation." (PMID 36009479, 2022). "COBLL1 gene rs7607980 polymorphism was associated with insulin resistance (HOMA-IR)." (PMID 36009479, 2022). "Because the association between the COBLL1 C allele and lower insulin resistance is present early in life and thus it is likely to persist over time, it would be interesting to examine if the changes in insulin levels are also associated with a reduction of the long-term risk for type 2 diabetes." (PMID 23463496, 2013). "It has been shown that SNP rs7607980 in the COBLL1 gene affects insulin resistance." (PMID 36009479, 2022). "The remaining loci were associated with ISI, including 6 loci not previously implicated in post-challenge insulin resistance: MTOR, COBLL1, PPARG, C5orf67, FAM101A, SLC2A4." (PMID 37291194, 2023).
type 2 diabetes (8 papers, 2013 to 2024). "The COBLL1 gene has been implicated in human central obesity, fasting insulin levels, type 2 diabetes, and blood lipid profiles." (PMID 38699158, 2024). "Genome-wide association studies have revealed the localization of the human COBLL1 gene in genomic regions associated with metabolism, including high-density cholesterol, triglyceride metabolism, insulin levels, type 2 diabetes, and other metabolic disorders." (PMID 38699158, 2024). "rs7607980 is a missense variant in COBLL1 previously linked to fasting blood insulin and Type 2 diabetes." (PMID 33175840, 2020). "In analyses of the 12 metabolic phenotypes the strongest novel associations were demonstrated between the CD300LG R82C missense variant and fasting HDL-cholesterol (β = −0.18, p = 7.2 × 10−8) and the COBLL1 rs7607980 variant and type 2 diabetes (OR 0.80, p = 7.2 × 10−8)." (PMID 23160641, 2013). "COBLL1 N939D found here is in partial LD with these variants (HapMap release 27: r2 = 0.18 and r2 = 0.20, respectively) and conditional analysis showed that COBLL1 N939D carries the effect on type 2 diabetes when conditioning on rs10195252 or rs3923113." (PMID 23160641, 2013). "COBLL1 (cordon-bleu WH2 repeat protein-like 1) gene is associated with neural tube formation, central obesity, fasting insulin, type 2 diabetes risk, blood lipids, CVD risk, gastric cancer, prostate cancer, and leukemia." (PMID 36835164, 2023). "The variants N939D in COBLL1 and M2290V in MACF1 were associated with type 2 diabetes, yet non-coding SNPs in these loci have previously been associated with other metabolic phenotypes." (PMID 23160641, 2013). "We identified a low-frequency amino-acid polymorphism in CD300LG associated with fasting HDL-cholesterol and two common amino-acid polymorphisms in COBLL1 and MACF1 associated with type 2 diabetes." (PMID 23160641, 2013). "Genes C2orf16, ZNF512 and COBLL1 were also previously reported, as was SLC39A8 in chromosome (CHR) 4, which plays a role in hypertension and has been found to be associated to type-2 diabetes." (PMID 34145383, 2021). "A low-frequency (MAF 3.5%) non-synonymous (R82C) polymorphism in CD300LG was associated with lower fasting levels of serum HDL-cholesterol while two common (MAF 12.5% and 23.4%, respectively) non-synonymous polymorphisms in COBLL1 and MACF1 were associated with type 2 diabetes." (PMID 23160641, 2013). "In the COBLL1 locus the intergenic rs10195252 is reported to associate with fasting triacylglycerol and waist-to-hip ratio in women while the intergenic rs3923113 was reported to associate with type 2 diabetes in a GWAS in individuals of South Asian ancestry." (PMID 23160641, 2013).
prostate carcinoma (5 papers, 2009 to 2025). A carcinoma that arises from epithelial cells of the prostate gland. "The most upregulated gene in SHP2R138Q-expressing cells, considering both SHP2-driven effects and EGF-induced effects, was COBLL1, which is involved in the oncogenesis of prostate cancer and chronic lymphocytic leukemia." (PMID 40631144, 2025). "Furthermore, COBLL1 has been identified as related to drug resistance in chronic myeloid leukemia, gestational diabetes, and prostate cancer." (PMID 40045635, 2025). "Although Cobll1 has been shown to be linked to diverse processes of cancer formation and progression including CML, CLL, and prostate cancer, its molecular regulation has not been fully understood." (PMID 35352878, 2022).
chronic lymphocytic leukemia (3 papers, 2022 to 2024). "COBLL1 expression is associated with survival in chronic lymphocytic leukemia and has also been linked to survival probability in several other cancer types including chronic myeloid leukemia." (PMID 39026229, 2024). "Patients with CML and chronic lymphocytic leukemia (CLL) possessing high Cobll1 expression have shown poor clinical outcomes." (PMID 35352878, 2022).
chronic myeloid leukemia (3 papers, 2022 to 2025). "Cobll1 affects blast crisis (BC) progression and tyrosine kinase inhibitor (TKI) resistance in chronic myeloid leukemia (CML)." (PMID 35352878, 2022).
Abdominal obesity (2 papers, 2023 to 2024). Excessive fat around the stomach and abdomen. "The major T allele of COBLL1 rs6717858 is associated with abdominal obesity, body fat, WC, and blood lipid accumulation, especially in women." (PMID 36835164, 2023).
diabetes (2 papers, 2022 to 2023). "We analyzed the association between COBLL1 and GRB14 mRNA expression and metabolic phenotypes, including diabetes, lipid, and inflammatory parameters, as well as adipokines." (PMID 35955692, 2022).
Hypertension (2 papers, 2020 to 2021). The presence of chronic increased pressure in the systemic arterial system. "The 2 variants with this pattern of association include (i) COBLL1:p.N497D which is associated with decreased TG levels and decreased risk of T2D in both HUNT and UK Biobank and of liver disease in HUNT and (ii) LPL:p.S474X which is associated with decreased risk of CAD, T2D, and hypertension." (PMID 33339817, 2020).
Tourette syndrome (2 papers, 2018 to 2020). A neurologic disorder caused by defective metabolism of the neurotransmitters in the brain. "We discuss the association of SCN2A, SCN3A, GRB14, COBLL1 and SCL38A11 deletions with ASD and Tourette syndrome and possible implications for treatment." (PMID 30071822, 2018).
Alzheimer disease (1 paper, 2022). A progressive, neurodegenerative disease characterized by loss of function and death of nerve cells in several areas of the brain leading to loss of cognitive function such as memory and language. "Other genes in analysis (JMY, ZNF525, and COBLL1) were not previously associated with Alzheimer’s disease." (PMID 35626321, 2022).
colorectal carcinoma (1 paper, 2021). A malignant epithelial neoplasm that arises from the colon or rectum and invades through the muscularis mucosa into the submucosa. "Cordon-bleu WH2 repeat protein like 1 (COBLL1) role in the cell are morphogenesis, interactions, growth, and phosphorylation and it is related to diseases such as organismal death, colorectal carcinomagenesis, colorectal carcinoma, and gastric epithelial cancer amongst others." (PMID 34778377, 2021).
coronary artery disease (1 paper, 2022). "It is important to note that the interactions between F2 rs3136441, LPA rs55730499, STARD3 rs881844, SCARB1 rs838880, and COBLL1 rs12328675 showed a strong contribution to the risk of coronary artery disease." (PMID 35203469, 2022).
fatty liver disease (1 paper, 2024). A reversible condition wherein large vacuoles of triglyceride fat accumulate in liver cells via the process of steatosis. "Other previously unreported variants associated with lipid traits and fatty liver disease, including rs2792735 in GPAM, rs2980888 in TRIB1, rs13389219 in COBLL1, rs8178824 in APOH and rs339969 in ICE2." (PMID 38632349, 2024).
malignant mesothelioma (1 paper, 2013). A malignant neoplasm of the pleura or peritoneum, arising from mesothelial cells. "Moreover, COBLL1 is a negative regulator of apoptosis in malignant mesothelioma cells and its expression is associated with a relatively better prognosis." (PMID 24004562, 2013).
metabolic syndrome (1 paper, 2022). A cluster of metabolic risk factors for CARDIOVASCULAR DISEASES and TYPE 2 DIABETES MELLITUS. "Previous studies have shown that COBLL1 and IRS1 gene polymorphisms are associated with T2DM risk and the development of metabolic syndrome." (PMID 36009479, 2022).
myeloma (1 paper, 2022). "In agreement with the gene model, compared with bortezomib-sensitive myeloma cell lines (negative control), there was an increase in mRNA expression of SCN9A, RGS7, NTF3, HSPB8, and ZBED1 and a decrease in CCND1, COBLL1, EGR1, OCLN, and ZBED1 mRNA expression of bortezomib-resistant cell lines." (PMID 36467498, 2022).
non-alcoholic fatty liver disease (1 paper, 2022). "For instance, COBLL1, a gene with liver-specific colocalization for fasting insulin and BMI and previously associated with non-alcoholic fatty liver disease, showed decreased expression under both atorvastatin and metformin in the liver." (PMID 35292083, 2022). "For example, two genes previously associated with non-alcoholic fatty liver disease, or NAFLD (COBLL1 and PNPLA3), show colocalization in the liver, the former with fasting insulin and BMI and the latter with T2D, HDL, and TG, implicating them as shared genetic associations for IR/T2D and NAFLD." (PMID 35292083, 2022).
Simpson-Golabi-Behmel syndrome (1 paper, 2024). Simpson-Golabi-Behmel syndrome is a rare X-linked multiple congenital anomalies syndrome, characterized by pre- and postnatal overgrowth, distinctive craniofacial features, variable congenital malformations, organomegaly and an increased tumor risk. "Loss of COBLL1 results in excessive lipid accumulation and increased lipolysis in preadipocytes (Simpson-Golabi-Behmel syndrome), suggesting that COBLL1 may have a crucial role in lipid metabolism." (PMID 38699158, 2024).
viral infection (1 paper, 2016). "The primary B cell infection with this virus unequivocally demonstrated that the RBPJ BM EBNA3C virus is completely unable to repress ADAM28, ADAMDEC1 and COBLL1, providing compelling evidence that the EBNA3C:RBPJ interaction is essential in the context of viral infection." (PMID 26751214, 2016). "In conclusion, these results showed that the ability of EBNA3C to interact with RBPJ is not only essential for repression in transient reporter assays, but also for the repression of the endogenous COBLL1 and ADAM28-ADAMDEC1 locus in the context of viral infection." (PMID 26751214, 2016).
cancer (4 papers, 2022 to 2024). A tumor composed of atypical neoplastic, often pleomorphic cells that invade other tissues. "The COBLL1 locus is genetically associated with the development of metabolic diseases and some cancers." (PMID 36009479, 2022). "Previous studies have shown that the COBLL1 locus is genetically linked to carbohydrate–lipid metabolism, the development of metabolic diseases, and some cancers." (PMID 36009479, 2022).